PTPRT (protein tyrosine phosphatase receptor type T)
Description:
May be involved in both signal transduction and cellular adhesion in the CNS.
Synonyms: R-PTP-T; RPTP-rho; KIAA0283; RPTPrho
Tractability: Small molecule: a structure with a bound ligand is known. Antibody: its Gene Ontology location is reachable by antibodies, with high confidence; UniProt predicts a signal peptide or a membrane-spanning region. PROTAC: its protein half-life has been measured.
Gene: Protein-coding gene on chromosome 20 (42,072,752 to 43,189,970, reverse strand). Ensembl gene ENSG00000196090.
Subcellular location: Membrane
Gene Ontology:
Molecular function: alpha-catenin binding; beta-catenin binding; cadherin binding; delta-catenin binding; gamma-catenin binding; protein binding; protein homodimerization activity; protein phosphatase binding; protein tyrosine phosphatase activity; STAT family protein binding; transmembrane receptor protein tyrosine phosphatase activity; alpha-actinin binding; thiolester hydrolase activity
Biological process: cell surface receptor protein tyrosine kinase signaling pathway; cellular response to interleukin-6; homophilic cell-cell adhesion; negative regulation of cell migration; negative regulation of receptor signaling pathway via STAT; protein dephosphorylation; cell adhesion; neuron projection development; signal transduction
Cellular component: cell surface; plasma membrane; membrane
Genetic constraint (gnomAD): Loss-of-function variants: 52 observed, 165.84 expected, observed/expected ratio (o/e) 0.31, 90% interval 0.25 to 0.4. The upper end of that interval is the gene's LOEUF score, 0.4, which puts it in group 1 of 6, group 1 being the genes least tolerant of losing a copy. Missense variants: 1,519 observed, 1,904 expected, observed/expected ratio (o/e) 0.8, 90% interval 0.76 to 0.83. Synonymous variants: 775 observed, 747.78 expected, observed/expected ratio (o/e) 1.04, 90% interval 0.98 to 1.1.
Cancer hallmarks: suppression of growth (promotes)
Homologues: Orthologues: macaque PTPRT (99% identical), dog PTPRT (99% identical), chimpanzee PTPRT (99% identical), pig PTPRT (99% identical), rat Ptprt (99% identical), mouse Ptprt (98% identical), rabbit PTPRT (96% identical), guinea pig PTPRT (95% identical), tropical clawed frog ptprt (85% identical), zebrafish ptprt (83% identical), zebrafish ptprt (38% identical). Paralogues in human: PTPRM (66% identical), PTPRK (58% identical), PTPRU (52% identical), PTPRD (29% identical), PTPRF (29% identical), PTPRS (28% identical), PTPRZ1 (23% identical), PTPRG (20% identical), PTPRB (19% identical), PTPRC (19% identical), PTPRA (17% identical), PTPRE (17% identical), and 23 more.
Diseases named in the same sentence as PTPRT in open-access papers:
PTPRT is named in the same sentence as 71 diseases in open-access papers, as found by Europe PMC text mining. Sharing a sentence is not in itself a finding about the gene and the disease. The quoted sentences say what the papers report.
melanoma (12 papers, 2014 to 2025). A malignant, usually aggressive tumor composed of atypical, neoplastic melanocytes. "Protein tyrosine phosphatase receptor type T (PTPRT), which is a well‐known phosphatase and mutates frequently in melanoma and non‐small cell lung cancer (NSCLC)." (PMID 34862763, 2022). "The markedly higher TMB and NB were found in melanoma patients with PTPRT mutations (median TMB: 4.99 vs. 2.61, median NB: 5.01 vs. 2.98, both p < 0.001)." (PMID 34862763, 2022). "In the WES melanoma cohort, patients with PTPRT mutations harbored a significantly elevated ICI response rate (40.5% vs. 28.6%, p = 0.036) and a prolonged survival outcome (35.3 vs. 24.9 months, p = 0.006)." (PMID 34862763, 2022). "We conducted an integrative immunotherapy analysis of PTPRT mutations in melanoma and NSCLC patients with both WES and targeted sequencing." (PMID 34862763, 2022). "In summary, in this integrative study, PTPRT mutation was identified as a putative strong biomarker to infer immune checkpoint‐based treatment responses in melanoma, NSCLC, even across multiple cancers." (PMID 34862763, 2022). "Considering the crucial roles of PTPRT mutations for immunotherapy prognosis evaluation, we explored the potential mechanisms behind PTPRT mutations in melanoma." (PMID 34862763, 2022). "The elevated TMB of PTPRT mutations was also observed in pan‐cancer, melanoma, and NSCLC cohorts (all p < 0.001)." (PMID 34862763, 2022). "Compared with PTPRT wild-type, PTPRT nonsynonymous mutations were associated with better OS in melanoma (N=596) and in pan-cancer (N=2129), and was associated with better PFS in NSCLC (N=510)." (PMID 34123798, 2021). "In melanoma, mutations in PTPRT, such as E324K, which create neoepitopes, may be associated with better outcomes for patients on immunotherapy." (PMID 35494035, 2022). "Our investigation indicates that PTPRT mutations may be considered as a potential indicator for assessing ICI efficacy in melanoma and NSCLC, even across multiple cancers." (PMID 34862763, 2022). "PTPRT is mutated in various cancers, such as melanoma and gastric cancer." (PMID 35789644, 2022). "Our study suggests that PTPRT mutations may serve as a strong biomarker to assess ICI efficacy in melanoma and NSCLC, even across multiple cancers." (PMID 34862763, 2022). "Therefore, PTPRT mutations may be an alternative surrogate for predicting ICI response in melanoma and NSCLC." (PMID 34862763, 2022). "Based on the mutational profile of The Cancer Genome Atlas (TCGA) derived from the cBioPortal, the alteration rate of PTPRT was 29.9% in melanoma and >10% in patients with lung adenocarcinoma, stomach, colorectal, uterine, and esophageal cancers." (PMID 34862763, 2022). "We observed that PTPRT was the most frequently mutated gene in the PTP family, contributing to 126 of 631 melanoma samples (20.0%)." (PMID 34862763, 2022). "By using the same pooled melanoma and NSCLC cohorts, we also discovered other mutations of the genes FAT1, COL3A1, NRAS, NARS2, DCC, and PTPRT were associated with better ICI response and outcome." (PMID 35884556, 2022). "In this study, we first integrated ICI‐treated melanoma and NSCLC samples with whole‐exome sequencing to explore the link between PTPRT mutation and ICI survival." (PMID 34862763, 2022). "The consistent results of PTPRT mutations with elevated TMB and NB were also obtained based on the melanoma samples from the TCGA cohort (both p < 0.001)." (PMID 34862763, 2022). "Importantly, the association between PTPRT mutations and improved ICI responses in both NSCLC and melanoma cohorts suggested its pan-cancer predictive value." (PMID 40808963, 2025). "Furthermore, PTPRT-mutation correlated with favorable response, higher TMB and lymphocyte infiltration in ICI-treated melanoma and NSCLC patients." (PMID 39238637, 2024). "In addition, PTPRT has been determined as a significantly mutated gene (SMG) in lung squamous cell carcinoma, colorectal cancer, and melanoma." (PMID 34862763, 2022).
melanoma (continued). "Besides melanoma and NSCLC, PTPRT was also frequently mutated in other several cancers, such as stomach, colorectal, uterine, and esophageal cancers, as described by the cBioPortal TCGA data." (PMID 34862763, 2022).
colorectal cancer (11 papers, 2014 to 2024). A primary or metastatic malignant neoplasm that affects the colon or rectum. "In the first comprehensive mutational analysis of the entire PTP family in human cancers, we identified protein tyrosine phosphatase receptor-T (PTPRT) as the most frequently mutated PTP in colorectal cancers (CRC)." (PMID 27447856, 2017). "Protein tyrosine phosphatase receptor T (PTPRT) is frequently mutated in a variety of human cancers including colorectal cancer." (PMID 27447856, 2017). "Interestingly, the authors also demonstrated that the most frequent genetically mutated tyrosine phosphatase gene was PTPRT in their colorectal cancer (CRC) cohort." (PMID 38475971, 2024). "Recent studies have reported that PTPRT is involved in the early metastatic seeding of colorectal cancer; however, the correlation between PTPRT and metastasis in other types of cancer has not been revealed." (PMID 35789644, 2022). "PTPRT plays in suppressing tumor growth and cell adhesion in various cancers, including colorectal cancer, hepatocellular carcinoma, prostate cancer, lung squamous cell carcinoma, esophageal squamous cell carcinoma, and glioma." (PMID 34414233, 2021). "They showed PTPRT specifically dephosphorylated STAT3 at a tyrosine at amino acid Y705 and overexpression of normal PTPRT in colorectal cancer cells reduced the expression of STAT3 target genes." (PMID 34414233, 2021). "PTPRT is an antioncogene and plays important roles in various cancers, including colorectal cancer, hepatocellular carcinoma, prostate cancer, lung squamous cell carcinoma, and glioma." (PMID 34414233, 2021). "Leptin suppresses food intake by activating STAT3 phosphorylation in the hypothalamus; our previous study shows that PTPRT dephosphorylates STAT3 in colorectal cancers." (PMID 24949727, 2014). "PTPRT has recently been reported to be closely related to early metastasis of colorectal cancer." (PMID 31570735, 2019). "Previous studies on the mutational analysis of the tyrosine phosphatase gene superfamily in human cancers identified 83 somatic mutations in six PTPs (PTPRF, PTPRG, PTPRT, PTPN3, PTPN13, PTPN14), affecting 26% of colorectal cancers and a smaller fraction of lung, breast and gastric cancers." (PMID 27833130, 2016). "Moreover, PTPRT overexpression in these colorectal cancer cells inhibited their growth." (PMID 31065022, 2019). "Fusobacterium nucleatum, a gram-negative anaerobic bacillus, is mainly associated with colorectal cancer patients positive for the CpG island methylator phenotype, although hypermethylation in genes such as MLH1, CDKN2A, MTSS1, RBM38, PKD1, PTPRT, and EYA4 has also been described." (PMID 37614819, 2023).
breast carcinoma (10 papers, 2016 to 2025). "In breast cancer, the combined mutation frequency of PTPRT and PIK3CA in metastatic breast cancer was significantly higher than in primary cancer (q = 0.025)." (PMID 35789644, 2022). "This was confirmed in breast cancer, and PTPRT was negatively associated with STAT3, while the promoter methylation level of PTPRT was positively associated with STAT3 based on TCGA data." (PMID 34414233, 2021). "Candidate predictive biomarkers to date include elevated CRP in pancreatic and breast cancers, PTPRT/D mutations in HNC, and a JAK1 S703I mutation in HCC, and assessments of biologically plausible biomarkers that predict clinical responses are needed." (PMID 33521321, 2020). "Intriguingly, among these downregulated genes, CLEC10A and PTPRT have been demonstrated as poor prognostic factors when their expressions were reduced in breast cancer, suggesting a plausible negative regulatory mechanism of these miRNAs in our TRM signature." (PMID 35805995, 2022). "Luminal A breast cancer patients were of the highest level of PTPRT, which was higher than that in normal-like breast cancer (p < 0.05)." (PMID 34414233, 2021). "Based on TCGA data, the promoter methylation level of PTPRT was higher in breast cancer tissues than those in adjacent normal breast tissue (0.067 vs. 0.039, p = 1.62E − 12)." (PMID 34414233, 2021). "Our study comprehensively searched available databases to analyze the clinical role of PTPRT in breast cancer." (PMID 34414233, 2021). "In our study, not only TCGA but also GEO data were included to explore the role of PTPRT in breast cancer." (PMID 34414233, 2021). "In order to analyze the clinical role of PTPRT in breast cancer, we comprehensively searched available databases to summarize the treatment predictive and prognostic values of PTPRT." (PMID 34414233, 2021). "According to bc-GenExMiner v4.3, estrogen receptor or progesterone receptor-positive (IHC) breast cancer patients were with higher PTPRT levels, while HER2+ (IHC) breast cancer patients were with lower PTPRT level." (PMID 34414233, 2021). "Future studies are needed about how PTPRT affects the drug effectiveness and breast cancer prognosis, as well as microtubule dynamics and cell cycle." (PMID 34414233, 2021). "The expression level of PTPRT in stage 1 to 4 breast cancer tissues was lower than that in adjacent normal breast tissue (stage 1 vs. stage 2 vs. stage 3 vs. stage 4: 3.68 vs. 2.01 vs. 1.92 vs. 0.83)." (PMID 34414233, 2021). "HER2+ and basal-like breast cancer were of lower PTPRT level than that in normal-like breast cancer, and basal-like breast cancer was of the lowest PTPRT expression level." (PMID 34414233, 2021). "The prognostic values of PTPRT were consistent across different molecular types of breast cancer." (PMID 34414233, 2021). "PTPRT might inhibit tumor growth via disrupting the microtubule dynamics and cell cycle in breast cancer." (PMID 34414233, 2021). "PTPRT might be an inhibitor of tumor growth via disrupting the microtubule dynamics and cell cycle in breast cancer." (PMID 34414233, 2021). "Our study comprehensively analyzed the role of PTPRT in breast cancer." (PMID 34414233, 2021). "We found PTPRT was an antioncogene and could be used to distinguish different stages, age groups, molecular types, and grades for breast cancer." (PMID 34414233, 2021). "We confirmed that PTPRT might inhibit tumor growth in breast cancer, which might be due to microtubule dynamics." (PMID 34414233, 2021). "Third, PTPRT might be an inhibitor of tumor growth via disrupting the microtubule dynamics and cell cycle in breast cancer." (PMID 34414233, 2021). "PTPRT could be used as biomarkers to predict taxane, anthracycline, and ixabepilone effectiveness and prognosis for breast cancer patients." (PMID 34414233, 2021).
breast carcinoma (continued). "Furthermore, PTPRT was negatively correlated with BIRC5 in other cancer types such as breast carcinoma (BRCA, R = -0.497, P < 0.0001), pancreatic adenocarcinoma (PAAD, R = -0.371, P < 0.0001), stomach adenocarcinoma (STAD, R = -0.279, P < 0.0001), and mesothelioma (MESO, R = -0.465, P < 0.001)." (PMID 38216925, 2024). "All these data suggest PTPRT might inhibit tumor growth in breast cancer as a tumor suppressor." (PMID 34414233, 2021). "The role of PTPRT in breast cancer was not comprehensively explored and well analyzed." (PMID 34414233, 2021). "PTPRT expression was not affected by ER or HER2 expression, but PTPRT could distinguish Luminal A and TNBC, HER2+ breast cancer." (PMID 34414233, 2021).
lung adenocarcinoma (7 papers, 2016 to 2024). A carcinoma that arises from the lung and is characterized by the presence of malignant glandular epithelial cells. "Another study involved in lung adenocarcinoma revealed that the African American patients had a markedly elevated PTPRT mutations than the European American patients and suggested the clinical significance for the recruitment of the minority population in clinical trials." (PMID 34862763, 2022). "Cell cycle-related genes (BIRC5, OIP5, and CDCA3, etc.)were specifically upregulated in PTPRT-low lung adenocarcinoma (LUAD)." (PMID 38216925, 2024). "In this study, through analysis of the gene expression data of TCGA lung adenocarcinoma (LUAD) and lung squamous cell carcinoma (LUSC) from The Cancer Genome Atlas (TCGA) database, we depicted the genes and pathways associated with PTPRT downregulation." (PMID 38216925, 2024). "Here we show results from a targeted sequencing panel using NCI-MD Case Control Study patient samples and reveal a significantly higher prevalence of PTPRT and JAK2 mutations in lung adenocarcinomas among African Americans compared with European Americans." (PMID 31844068, 2019). "Here, we report two genes, PTPRT and JAK2, that are recurrently mutated in lung adenocarcinoma (LUAD) among AAs." (PMID 31844068, 2019). "PTPRT mutations were detected in 24 cancer types, including SKCM, gastric adenocarcinoma, uterine corpus endometrial carcinoma, colorectal adenocarcinoma, and lung adenocarcinoma." (PMID 35789644, 2022).
lung cancer (6 papers, 2018 to 2024). A malignant neoplasm involving the lung. "PTPRT was found to be frequently mutated in multiple cancer types, especially in cutaneous melanoma, gastric adenocarcinoma, endometrial cancer, and lung cancer." (PMID 38216925, 2024). "Furthermore, PTPRT downregulation was associated with elevated tumour mutation burden and tumour neoantigen burden in lung cancer, indicating the potential influence on tumour immunogenicity." (PMID 38216925, 2024). "Together, these findings suggested that the expression level of PTPRT was associated with tumour immunogenicity in lung cancer, and might be predictive of the responses to ICI therapies." (PMID 38216925, 2024). "Our findings uncovered the essential roles of PTPRT in the regulation of proliferation, migration, and invasion of LUAD, and highlighted the clinical significance of PTPRT downregulation in lung cancer." (PMID 38216925, 2024). "We then validated the functional impacts of PTPRT expression on cell proliferation, migration and invasion through in vitro experiments using lung cancer cell lines." (PMID 38216925, 2024). "Together, these results showed that PTPRT expression was significantly correlated with multiple genes in the cell adhesion and cell cycle pathways in lung cancer, especially in LUAD." (PMID 38216925, 2024). "PTPRT was found to be downregulated in tumours and lung cancer cell lines compared to normal samples." (PMID 38216925, 2024). "Our previous study have found that PTPRT was downregulated in a variety of cancers, but the effects and mechanisms of PTPRT downregulation on proliferation, migration, invasion, and tumour immunogenicity of lung cancer are still poorly understood." (PMID 38216925, 2024). "Knockdown and overexpress of PTPRT in lung cancer cell lines were performed to explore the function of PTPRT in vitro." (PMID 38216925, 2024). "In addition, low PTPRT expression level was correlated with worse prognosis of lung cancer and several other cancer types." (PMID 38216925, 2024).